MMP2 (matrix metallopeptidase 2)
Diseases named in the same sentence as MMP2 in open-access papers (continued):
Sharing a sentence is not in itself a finding about the gene and the disease.
bladder cancer (continued). "This study aims to evaluate the combination effects of cisplatin, gemcitabine, and the APC/C inhibitor proTAME on cell migration as well as MMP2 and MMP9 expression in bladder cancer (RT4 cells) and normal epithelial cells (ARPE-19) as the control." (PMID 40136519, 2025). "Comparing MMP2 and MMP9, as potential bladder cancer biomarkers, both are suitable for T2 or higher stages of the disease, while both have failed at early stages." (PMID 41228251, 2025). "This phytomolecule has been shown to inhibit the migration and viability of TSGH-8301 bladder cancer cells by downregulating the AKT and MMP2 cell signaling pathways." (PMID 40005959, 2025). "In bladder cancer studies, gallic acid has been shown to modulate cell proliferation via the PI3K/AKT and MAPK/ERK pathways, as well as inhibit bladder cancer cell invasion and migration through regulation of p-AKT/MMP2 signaling." (PMID 39045282, 2024). "Osthole also decreased the levels of MMP2 and MMP9 proteins, which are involved in the bladder cancer cells invasion and migration abilities." (PMID 37069622, 2023). "The upregulation of cytokeratin 18 and cytokeratin 19 (epithelial markers) and the downregulation of vimentin, N-cadherin, MMP2, and ZEB1 (mesenchymal markers) were observed in the bone metastatic T24-B bladder cancer cells." (PMID 37627900, 2023). "What still remains disputable is the potential significance of determination of the concentration of MMP-2 and MMP-9 in urine as an important predictor of urinary bladder cancer progression." (PMID 36979935, 2023). "Previous studies have shown that low levels of miR-124 upregulated MMP-2 and MMP-9 in bladder cancer cells and favored their invasion." (PMID 35620289, 2022). "Focal adhesive complex, MMP2, MMP9, and angiogenic-related proteins were decreased, while FXR was overexpressed in bladder cancer cells." (PMID 35563650, 2022). "COL6A3 silencing suppresses the expression of MMP-2, MMP-9, and vimentin, then participates in the process of inhibiting EMT of bladder cancer cells." (PMID 35774273, 2022). "Although the anticancer activities of naringenin have been widely reported, recent experimental evidence indicates that naringenin inhibits TSGH-8301 bladder cancer cell migration via deactivation of AKT signaling and MMP-2 downregulation." (PMID 33996570, 2021). "T24-Exos or J82-Exos also induced the expression of the EMT-transcription factors Slug, Snail, Twist and Zeb2, which ultimately suppressed E-cadherin expression but promoted N-cadherin, vimentin, MMP2 and MMP9 expression in bladder cancer cells." (PMID 32517366, 2020). "In the J82 bladder cancer cell, honokiol repressed the expression of SRC-3, MMP-2, and Twist1 genes which were involved in cancer cell invasion." (PMID 31877856, 2019). "In bladder cancer, antrocin inhibits migration and invasion by suppressing the ERK/FAK/paxillin and ERK/c-Fos/MMP-2 signaling pathways." (PMID 30602706, 2018). "As a result of inducing transactivation or transrepression of GR by dexamethasone, up-regulation of FKPB51 and GILZ or down-regulation of NF-κB and AP-1 as well as MMP-2, MMP-9, IL-6, and VEGF, respectively, has been documented in bladder cancer cells." (PMID 30518063, 2018). "For instance, there are three edges connecting the genes with the pathway ‘hsa05219: Bladder cancer’ together with the labels of “C N VEGFA”, “C N MMP2” and “C MDM2”." (PMID 28340554, 2017). "Using MMP-2/9 antibodies and ERK inhibitor PD98059, we validate that Derlin-1 induces bladder cancer invasion through activation of ERK signaling, which in turn upregulates MMP-2 and MMP-9 protein expression." (PMID 28178653, 2017). "MMP-2 and MMP-9 were reported to play important roles in bladder cancer cell invasion and metastasis." (PMID 28178653, 2017).
bladder cancer (continued). "Loss of expression of miRNA-141 and miRNA-200b was associated with increased invasion and migration ability, upregulated MMP-2, MMP-9, vimentin and N-cadherin expression, and downregulated E-cadherin expression in bladder cancer cell lines." (PMID 25884322, 2015). "We chose five candidate genes (PTPRF, MMP2, VEGFA, CDH1 and CLDN7) that were detected differential expression by Cuffdiff and involved in Bladder cancer pathway, cell adhesion molecules (CAMs) pathway and focal adhesion pathway." (PMID 24622401, 2014). "On the other hand, ROCK1-induced high level of c-Met, MMP2 and MMP9, which enhances migration and invasion of bladder cancer cells." (PMID 24180482, 2013). "Our results demonstrated that cantharidin potently inhibited the migration and invasion of TSGH-8301 human bladder carcinoma cells through inhibiting the p38 and JNK1/2-modulated MMP-2/-9 signaling in vitro." (PMID 23431332, 2013). "MMP-2 and MMP-9 were highly expressed in bladder cancer metastasis, so the NDRG2 likely inhibited the metastasis of bladder cancer by regulating the expression of MMP-2 and MMP-9." (PMID 24146910, 2013). "We suspected that the expression of NDRG2 significantly suppresses the MMP-2 and MMP-9 by regulating the NF-kB signaling in the bladder cancer cells." (PMID 24146910, 2013). "In previous studies, p38 MAPK activation was demonstrated to regulate MMP2, MMP9 the activity of c-Met and can promote invasion of bladder cancer." (PMID 24180482, 2013). "RECK is a crucial MMP-2 repressor and RECK expression was previously reported to be down regulated in bladder cancer tissues compared to normal urothelium." (PMID 23226455, 2012). "Urinary MMP-9 levels, serum MMP-7 levels, and tissue levels of MMP-2, MMP-7, and MMP-14 have been identified as prognostic markers of bladder cancer." (PMID 22852097, 2012). "Our work confirms the importance of well-documented genes, such as MMP-2 and MT1-MMP, but also highlights several new proteases including MMP-28, whose localisation and function in early bladder cancer is under-investigated." (PMID 16465195, 2006). "For example, in bladder cancer cells, Capsaicin reduces the deacetylase of SIRT1, enhances the acetylation of cortactin and β-catenin, thereby reducing the activation of MMP-2 and MMP-9, and ultimately leads to the migration disturbance of bladder cancer cells." (PMID 40007993, 2025). "In human bladder cancer cells, genistein suppresses production or release of angiogenic proteins of PDGF-A, tissue factor (TF), and VEGF165, as well as enzymes involved in matrix degradation for MMP-2, MMP-9, and uPA." (PMID 38611849, 2024). "Moreover, p38 MAPK regulated the mRNA levels of MMP-2/9 by influencing both transcript stability and MMP-2/9 activity, which in turn affected the invasive capacity of bladder cancer." (PMID 38305808, 2024). "Moreover, MMP2, MMP9, MMP12, and MMP16-enriched KEGG pathways include “Bladder cancer, endocrine resistance, and relaxin signaling pathway”, etc.." (PMID 38560573, 2024). "Therefore, the aim of the study was to evaluate the expression and activity of matrix metalloproteinase 2 and 9 (MMP-2 and MMP-9) in urinary bladder cancer according to different stages." (PMID 36979935, 2023). "The expression of MMP2 and MMP9 was significantly reduced after FXR overexpression, which may inhibit invasion in human bladder cancer T24 cell." (PMID 35563650, 2022). "It was reported that the 5-year survival rate of MMP-2 positive cases was significantly lower than that of MMP-2 negative cases using immunohistochemical staining of 54 bladder cancer samples." (PMID 34868901, 2021).
bladder cancer (continued). "Finally, significantly increased levels of MMP-2 and MMP-9 were detected in the urine of bladder cancer patients, meaning that both MMPs also serve as bladder tumor-specific markers." (PMID 34199232, 2021). "In this study, we found that GSPs inhibited migration, invasion, and MMP-2/-9 secretion of both T24 and 5637 bladder cancer cells at noncytotoxic concentrations." (PMID 34354794, 2021). "The expression levels of MMP-2 and MMP-9 in bladder cancer cells transfected with Nucb2 shRNA was lowered, indicating that Nucb2 may affect cancer migration and invasion through the MMP-2 and MMP-9 signaling pathways." (PMID 34073612, 2021). "A previous study has reported that miR-29b suppresses angiogenesis by targeting of MMP-2 and VEGFA, although restoration of miR-29b could inhibit the metastasis and reverse the EMT in bladder cancer." (PMID 33407520, 2021). "Furthermore, the addition of MMP-2/9 antibody led to inhibition of tumor invasion, indicating that MMP expression in bladder cancers is directly responsible for it." (PMID 30850014, 2019). "Matrix metalloproteinase (MMP)-2 is the main enzymes involved in extra cellular matrix (ECM) degradation during EMT process, and considered to be important in tumor invasion and distal metastasis through blood vessel or lymphoid system in bladder cancer." (PMID 27058893, 2016). "We further demonstrated, using bladder cancer lines, that ZKSCAN3 knockdown resulted in significant reduction of cell viability, colony formation, cell migration, cell invasion, and the expression of MMP-2/MMP-9, as well as significant induction of apoptosis." (PMID 27447553, 2016). "In bladder cancer cells ZEB1 regulates vimentin, MMP2 and cytokeratins." (PMID 26098771, 2015). "To explore whether MMP-2 and MMP-9 are involved in regulation of human bladder cancer cell invasion, we first compared their expression levels between T24 and T24T cells." (PMID 25402510, 2015). "We next measured the level of MMP-2 and MMP-9 in this two bladder cancer cells." (PMID 24314030, 2013). "We confirmed that MMP2 and MMP9 were frequently up-regulated in bladder cancer tissues." (PMID 24180482, 2013). "Taken together, cantharidin was suggested to present antimetastatic potential via suppressing the levels of MMP-2 and MMP-9 expression that might be mediated by targeting the p38 and JNK1/2 MAPKs pathway in TSGH-8301 human bladder cancer cells." (PMID 23431332, 2013). "As we have revealed the down-regulation of ROCK1, MMP2 and MMP9 in bladder cancer tissues by IHC, we wanted to know whether knocking down miR-124-3p could result in the up-regulation of ROCK1, MMP2 and MMP9." (PMID 24180482, 2013). "ROCK1, MMP2, MMP9 were up-regulated in bladder cancer tissues." (PMID 24180482, 2013). "In bladder cancer, there again was a connection between high SPARC and poor prognosis but additionally, gene expression of SPARC correlated with matrix metalloproteinase-2 (MMP-2) expression." (PMID 22016635, 2011). "The ability of as-APF to significantly inhibit MMP2 mRNA and protein expression in T24 cells also suggests that as-APF may be able to decrease the invasive potential of bladder carcinoma cells as well as inhibit their proliferation." (PMID 21143984, 2010). "Furthermore, CXCR2 stimulation could promote bladder cancer cell migration and invasion by activating the PI3K/AKT-induced upregulation of MMP2/MMP9." (PMID 31681401, 2019). "In bladder cancer, CXCL5 was found to be significantly upregulated and the CXCL5/CXCR2 axis could promote the migration and invasion of bladder cancer cells by activating the PI3K/AKT-induced upregulation of MMP2/MMP9." (PMID 29743818, 2018). "However, 1,25D3 did not affect the expression of E-cadherin, MMP-2 nor MMP-9 in bladder cancer cell lines (data not shown)." (PMID 28947955, 2017).
bladder cancer (continued). "Unexpectedly, the results of the present study showed that 3 kinds of cytokines (IL-5, IL-20, and IL-28A) correlate with metastatic potential without altering cell proliferation, which results in bladder cancer cell migration and invasion through MMP-2 and MMP-9 expression." (PMID 22962576, 2012). "MMP2 overexpression correlated with bladder cancer stage, but not with grade." (PMID 16901349, 2006). "Given the critical role of MMP2 in bladder cancer invasion, as verified in our previous study, these findings are consistent with the possibility that the inhibitory effect of PHLPP2 on BC invasion, therefore downregulation of MMP2 by PHLPP2 may play a major role in its inhibition of BC invasion." (PMID 29930380, 2018). "In addition, we performed Immunohistochemical staining to assess the expression of MMP2 and MMP9 in human bladder cancer tissues, comparing with the paired non-tumor tissues." (PMID 24180482, 2013). "Moreover, the studies confirmed that cytokines might increase MMP-2 and MMP-9 expression and activation of NF-κB and AP-1, which regulate the MMP-9 promoter in muscle-invasive and non-muscle-invasive bladder cancer." (PMID 33923108, 2021).
cervical carcinoma (153 papers, 2002 to 2025). A carcinoma arising from either the exocervical squamous epithelium or the endocervical glandular epithelium. "Of the MMPs, MMP-2 acts as a key enzyme that has been linked to tumor metastasis and physiologic function in endometrial cancer and to lower overall survival in cervical cancer." (PMID 38205317, 2024). "In our study, MMP-2 expression, both tumoral and stromal, was associated with cervical cancer-related death." (PMID 32669083, 2020). "High PAK1 expression in cervical cancer is associated with its pathological features including angiogenesis, upregulation of MMP2, metastasis and poor prognosis." (PMID 31766427, 2019). "Bortezomib treatment reduces the migration and invasive capacity of a cervical carcinoma HeLa cell line, which was associated with a decrease in the intracellular expression of MMP2 and MMP9, and this is also observed in bortezomib treated chondrosarcoma cells." (PMID 36302993, 2023). "Interestingly, PVT1, one of lncRNA, was influenced by ALKBH5 silencing and associated with MMP2/9 expression in cervical cancer cells." (PMID 37639643, 2023). "MMP2 is associated with a higher risk of death from cervical cancer." (PMID 35389773, 2022). "Similarly, WIN 55212-2 treatment caused the down-regulation of MMP-2 in the cervical cancer cell in a dose-dependent manner." (PMID 29883990, 2019). "In addition, many clinical studies have emphasized the association of MMP expression with progression of cervical cancer, and many types of human tumor have been reported to be associated with increased expression of MMP-2." (PMID 28955234, 2017). "Therefore, we wonder whether heterologous expression of NaV1.6 channels in cervical cancer cells induces secretion of the gelatinases associated to cell invasion, i.e., MMP-2 and MMP-9." (PMID 30158710, 2018). "HDAC10 attenuated lymph node metastasis of cervical cancer by deacetylating the histones H3 and H4, which downregulated the expression of matrix metalloproteinase 2/9 (MMP2/9), thus mitigating migration and invasion." (PMID 40421455, 2025). "Previous studies have suggested the co‐participation of MMP‐2 and NaVs in migration and invasion activity in breast and cervical cancer." (PMID 40079158, 2025). "Upregulation of TIMP-1 forms the MMP-9 and MMP-2, which are inhibitory complexes that initiate anti-invasion of cervical cancer." (PMID 40008130, 2025). "In cervical cancer, quercetin potentiated cisplatin-induced apoptosis through coordinated downregulation of MMP2, METTL3, P-Glycoprotein (P-Gp), and ezrin." (PMID 40508204, 2025). "The expression of proteins and mRNA of MMP-2 is significantly elevated in human cervical cancer, while the release of MMP-9 induces angiogenesis and metastasis of these tumor cells." (PMID 39364049, 2024). "Resveratrol (20 μM, 40 μM) also suppressed the migratory and invasive abilities of cervical cancer cells by reducing MMP-2 and MMP-9 protein expression." (PMID 39335164, 2024). "miR-221/222 have been demonstrated to target the 3′ untranslated regions (UTR) of TIMP3 in cervical cancer and lead to an increase in the levels of MMP2 and MMP9, as well as the promotion of cell migration and invasion in cervical cancer." (PMID 38542164, 2024). "MMP-2 is one of the most important enzymes involved in cell migration, invasion, and tumor progression in endometrial and cervical carcinomas." (PMID 38205317, 2024). "Studies have demonstrated that knockdown of FTS (Fused Toes Homolog), an oncogene involved in cervical cancer pathogenesis, suppresses cell migration by downregulating MMP-2 and MMP-9 in cervical cancer." (PMID 37986152, 2023). "Concentrations of MMP-2 and MMP-9 correlate with the FIGO stage and are associated with poor prognosis in endometrial cancer, whereas in cervical cancer, MMP-9 has been associated with a better outcome." (PMID 36982551, 2023).